IL6 (interleukin 6)
Diseases named in the same sentence as IL6 in open-access papers (continued):
Sharing a sentence is not in itself a finding about the gene and the disease.
colitis (continued). "In summary, we demonstrated that modified PD could inhibit the increased inflammatory response and reduce the severity of colitis lesions through IL-6/STAT3 signaling pathway." (PMID 32517784, 2020). "Moreover, CA4P exacerbated the pathological features of colitis and significantly increased proinflammatory cytokines (IL-1β, IL-6, TNF-α) and inflammatory cells (neutrophil, lymphocyte, monocyte)." (PMID 32265711, 2020). "Equally interesting, SDS3 treatment of DSS-induced colitis mice significantly lowered IL-6 levels." (PMID 32271823, 2020). "The antigen invasion can activate the mucosal immune response, resulting in the release of proinflammatory cytokines from macrophages, such as tumor necrosis factor (TNF)-α, interleukin (IL)-1β, IL-6, and IL-8, which can exacerbate inflammatory severity and colitis." (PMID 33664740, 2020). "Evidences have demonstrated that H. pylori infection decreased the pro-inflammatory cytokines (TNF-α, IFN-γ, IL-1β, IL- 6, IL-17A and IL23) in colitis mouse models, and we also have reported that IL-6 and IL23 expression were down-regulated in H. pylori-infected chronic colitis mice." (PMID 33201893, 2020). "Moreover, MDEs were shown to downregulate the inflammatory process in part through the downregulation of key cytokines involved in colitis, such as IL-6 and TNF-α." (PMID 32858892, 2020). "Moreover, vitamin K has been shown to exert a protective effect against DSS-induced colitis in mice, through the inhibition of inflammation via IL-6 suppression in B cells." (PMID 32650452, 2020). "Colitis increased secretion of IFNγ and of IL-6 and tended to increase the secretion of TNFα." (PMID 32156075, 2020). "Besides driving the transcription of tumor-promoting genes such as c-Myc and cyclin-dependent kinase-6 (CDK6), a previous study explored a critical oncogenic role of NFATc2 in colitis-induced colon cancer by control of proinflammatory cytokine IL-6 production." (PMID 32041943, 2020). "The colon of EV-treated mice showed reduced levels of inflammatory cytokines (TNF-α, IFN-γ, IL-1β, IL-6 and iNOS) and elevated levels of an anti-inflammatory/regulatory cytokine (IL-10), compared to that of untreated mice with colitis and TSG-6-depleted EV-treated mice." (PMID 32040478, 2020). "Several studies have confirmed the A2BR pro-inflammatory roleby demonstrating that A2BR blockade with selective antagonistsdecreases IL-6 levels and neutrophil activation, resulting in decreased intestinaldamage in mice suffering from colitis or infected withC." (PMID 32725081, 2020). "Exercise significantly decreased TNBS-colitis macroscopic and microscopic severity, increased colonic blood flow, and attenuated plasma TNFα, IL-6, MCP-1, IL-1β and leptin levels in mice fed either a HFD (70% EAF) or a standard regular chow diet compared to their sedentary counterparts." (PMID 33603741, 2020). "The downregulated expression of IL-17A and IL-6 after DIM treatment was similar to that observed in mice with autoimmune diseases such as colitis and experimental autoimmune encephalomyelitis, in which IL-17A and IL-6 expression was also suppressed by DIM treatment." (PMID 33175869, 2020). "On the contrary, IL-6- and IL-22-mediated signaling pathways in the intestinal epithelium have been reported to modulate the proliferation of epithelial cells during the development of experimental colitis." (PMID 32369982, 2020). "The level of pro-inflammatory cytokines (TNFα, IL-1β and IL-6) in the blood serum, as well as IL-1β in the colon tissue of mice with colitis receiving algae extract, was lower than that in control animals, and the level of anti-inflammatory interleukin IL-10 was higher." (PMID 32486405, 2020). "IL-6 serum levels can be used as a prognostic marker in colitis." (PMID 32858892, 2020).
colitis (continued). "Oral treatments with the compounds significantly suppressed TNBS-induced expressions of IL-10, in addition to TNF-α, IL-6, and IL-1β in colon tissues, indicating that an anti-colitis activity of the compounds led to the resolution phase of TNBS-induced inflammation." (PMID 31619080, 2020). "In addition, these in vitro results were correlated with colonic IL-6 levels in DSS colitis because DSS is thought to disrupt the integrity of the mucosal barrier, which allows commensal bacteria to elicit TLR2 and TLR4 dependent inflammation." (PMID 31921214, 2019). "Indeed, treatment of mice with recombinant IL-6 protected the animals from DSS-induced colitis whereas treatment with a neutralizing IL-6 antibody aggravated DSS-induced colitis." (PMID 31694340, 2019). "DSS-colitis model mice produced high levels of the proinflammatory cytokines IL-1β, IL-6 and TNF-α, and B. adolescentis IF1-03 mice produced lower IL-1β, IL-6 and TNF-α, and elevated levels of the anti-inflammatory IL-10, compared to the DSS-colitis model and B. adolescentis IF1-11 protection mice." (PMID 30987344, 2019). "Studies have shown that the thalidomide treatment reduce TNF-α, IL-6 and IL-1β production, and histological analysis showed considerable reduction in neutrophil infiltration and mucosal damage in colon homogenate of experimental colitis." (PMID 31920668, 2019). "Astaxanthin induced improvements of various factors in DSS colitis, including: clinical and histological parameters, mRNA expression of inflammatory cytokines (IL-1β, IL-6, TNF-α, IL-36α and IL-36γ), activation of transcription factors NF-κB and AP-1 (c-Jun), and MAPK phosphorylation." (PMID 30705514, 2019). "Furthermore, S. cerevisiae has been shown to decrease inflammation in a mouse model of chemically-induced colitis; however, Il-6 can be produced by S. cerevisiae stimulus, in agreement with this research." (PMID 31482249, 2019). "Additionally, IL-6 is a key molecule contributing to neutrophil infiltration and cell apoptosis in colitis." (PMID 31182999, 2019). "DSS-induced mucosal inflammation or colitis was markedly increased in both IL-6-deficient mice and in mice lacking STAT3 in intestinal epithelial cells." (PMID 31798539, 2019). "We found that there were 15 analytes upregulated in both DSS and C. rodentium colitis, including innate immune cell-associated cytokines (G-CSF, IL-1β, TNF-α, LIF, and IL-6), chemokines (CCL2, CCL5, CCL11, CXCL2, CXCL8, CXCL9, MIP-1α, and MIP-1β), and Th1 (IFN-γ) and Th17 (IL-17) cytokines." (PMID 30972302, 2019). "Elevated levels of IL-6, IL-23, and IL-17 have been found in serum and colon mucosa of patients with UC, IL-23 exacerbates colon inflammation, and blocking IL-23 or IL-21 ameliorates colitis in mice, demonstrating that Th17 cells are key effector cells in UC." (PMID 31534467, 2019). "However, the mechanisms of action of thalidomide are not yet entirely clear, its benefit has primarily been ascribed to its roles as an anti-TNF-alpha agent and reduce TNF-α, IL-6 and IL-1β production in colon homogenate of experimental colitis." (PMID 31920668, 2019). "In C57BL/6 mice, β-sitosterol (20 mg/kg/day) administration for 56 days prevented the colon shortening (~8%) and reduced MPO activity in colon tissue (~35%), what led to a lower level of pro-inflammatory cytokines (IL-1β, TNF-α and IL-6) after colitis induction by high fat diet (60 Kcal% from fat)." (PMID 30987294, 2019). "Naringenin (4’,5,7-trihydroxy avanone-7-rhamnoglucoside), which belongs to the flavanone class, is shown to attenuate the severity of colitis by inhibiting myeloid derived suppressor cells (MDDCs), pro-inflammatory mediators, and the NF-kB/IL-6/STAT-3 cascade in colorectal tissues." (PMID 30764536, 2019).
colitis (continued). "At d3 and d5, significant differences were found in the plasma IL-6 concentrations among the three groups (F = 6.07, P = 0.008; F = 3.90, P = 0.036), and the rats in the colitis and pair-fed groups had significantly higher IL-6 concentrations than those in the control group (P < 0.05)." (PMID 31221091, 2019). "The results showed that quercetin alleviated the effects of C. rodentium-induced colitis, suppressed the production of pro-inflammatory cytokines, such as interleukin (IL)-17, tumor necrosis factor alpha, and IL-6 (p < 0.05), and promoted the production of IL-10 in the colon tissues (p < 0.05)." (PMID 31156598, 2019). "TNF-α and IL-6 serum levels were elevated in the colitis group as expected but were reduced by MRS." (PMID 31182999, 2019). "Indeed previous researches on experimental colitis have shown a positive correlation of TNF-α, IL-1β, and IL-6 levels in animal with colitis and the degree of colonic inflammation." (PMID 32641944, 2019). "Furthermore, the use of HDACs inhibitors (e.g., valproic acid) reduce disease severity and inhibit colonic proinflammatory cytokines (TNF-α, IFN-γ, and IL-6) in experimental murine colitis." (PMID 30915065, 2019). "In addition, FA-97 successfully prevented colitis by inhibiting the production of IL-1β, IL-6, TNF-α, IL-12, MIP-1α, and IL-17 in colons." (PMID 31969881, 2019). "With regard to the pro-inflammatory cytokines IL-1β, IL-6, and TNFα, our results are consistent with the data obtained by others, who showed that the level of pro-inflammatory cytokines increases in animals with colitis induced by exogenous agents." (PMID 31590413, 2019). "Similarly, L. reuteri treatment also decreased the serum levels of the inflammatory cytokines KC, TNF-a, IFN-γ, and IL-6 in the DSS colitis mice." (PMID 31214189, 2019). "In DSS colitis, increased levels of IL-6, CSF3, and IL-17 were further increased in Smox−/− mice." (PMID 29922289, 2018). "Furthermore, it has been reported that the DSS-induced colitis model is characterized by increased serum levels of IL-6, IL-17, and TNF-α and decreased levels of IL-4 and IL-10." (PMID 30393231, 2018). "Thus, ATF3 seems to play a more dominant role in the downstream of IL-22 signaling circuit in vivo, compared to a role in IL-6 signaling, as global ATF3−/− mice were more susceptible to DSS colitis and Citrobacter infection." (PMID 30455690, 2018). "Indeed, M2-associated genes (Arg1, IL-10, Fizz1, and Mrc1) were increased and M1-associated genes (IL-1β, IL-6, IL-12, and TNF-α) were decreased in colons of DSS colitis miR-155−/− mice." (PMID 29774026, 2018). "C57BL/6 mice had similar body weight loss in colitis independent of anti-IL-6 and sGP130Fc treatment under NCD and HFD conditions." (PMID 29695802, 2018). "We argue for a much more important role of IL-1β in development of colitis compared to IL-6." (PMID 30315268, 2018). "IL-6 plays important roles in tumor initiation via PLCγ1–mediated inflammatory response in colitis environment, and also after recovered colitis by removal of DSS, crosstalk between stat-3 and PLCγ1 is involved in tumor progression and development through apoptosis and proliferation." (PMID 29464031, 2018). "An in vivo study furthermore indicated that the administration of chemerin resulted in aggravation of DSS-induced colitis in mice by augmenting TNFα and IL-6 production, whereas a decrease in IL-10—producing anti-inflammatory macrophages could be detected." (PMID 30369924, 2018). "To investigate whether neutralising IL-6 or sIL-6Rα affects CAC, we injected anti-IL-6 antibody or the designer cytokine soluble GP130 (sGP130Fc) before the colitis phase at day 3 of the 1.5% AOM/DSS protocol in lean and obese C57BL/6 mice." (PMID 29695802, 2018). "Pro-inflammatory Tnf, Ifnγ, Il6 and Il1β mRNA expression levels were increased in colitis." (PMID 30315190, 2018).
colitis (continued). "IL-6 has pleotropic immunological effects and can either promote intestinal inflammation or provide mucosal protection in different murine models of colitis." (PMID 30356663, 2018). "Colon tissue from vehicle-treated mice had higher levels of TNF-α, IL-6, and IL-1β than did colon tissue from mice treated with the probiotic complex or the combination drug; the latter exerted the greatest effect on colitis (p < 0.001, p < 0.001, and p < 0.01, respectively)." (PMID 29466999, 2018). "Development of colitis is often associated with chronic inflammation, characterized by inflammatory cellular infiltration and series of cytokines secretion, such as TNF-α, IFN-γ, IL-6, IL-1β, IL-4, and IL-10." (PMID 29538417, 2018). "IL-1b and IL-6 production are increased in Nrf2−/− mice with dextran sulfate-induced colitis." (PMID 30180849, 2018). "DSS ingestion significantly increased the IL-6 level in colitis mice." (PMID 29554971, 2018). "This review aims to elucidate the role of chronic inflammation in colitis-associated CRC with a review regarding the contribution of inflammatory signaling pathways, including nuclear factor kappa B (NF-κB), IL-6/STAT3, cyclooxygenase-2 (COX-2)/PGE2, and IL-23/Th17." (PMID 28852270, 2017). "We further studied the role of IL-6 in DSS-colitis using IL-6-knockout mice." (PMID 29107964, 2017). "In the present study, the levels of TNF-α, IL-6, and IL-17 were tested in colitis mice." (PMID 28824631, 2017). "Moreover, colonic pro-inflammatory cytokines (TNF-α, IL-6, and IL-1β) induced by colitis were dramatically decreased by magnolol." (PMID 28726741, 2017). "Likewise, we also showed that IL-1β and IL-6 gene expression were significantly down-regulated at day 31 in experimental colitis mice when injected with TMSC[x4]." (PMID 28854223, 2017). "Interestingly, NZ-HO increased the production of IL-10, decreased inflammatory cell infiltration, and decreased expression of IL-6 and IL-1α in the colonic tissue of murine colitis models." (PMID 28179904, 2017). "Furthermore, the expression of proinflammatory mediators such as TNF-α, IL-1β, IL-6 and iNOS mRNA in the colons of WT colitis mice was markedly upregulated on day 7 and significantly higher than those of p85α+/− colitis mice." (PMID 28733636, 2017). "Finally, treatment with TMSC[x4] significantly reversed the mRNA levels of IL-1β and IL-6, although expression of all pro-inflammatory cytokines tested was induced in colitis mice." (PMID 28854223, 2017). "In addition, both SAMe and MTA can lower IL-6 expression and inhibit IL-6/STAT3 signaling in a colitis-associated colon cancer model and in human colon cancer cells." (PMID 29108270, 2017). "Body weight loss following DSS administration was also significantly lower in HFD-fed IL-6-knockout mice compared to HFD-fed wild type mice, suggesting that IL-6 may play a significant role in DSS-colitis of HFD-fed mice." (PMID 29107964, 2017). "In addition, in the chronic TNBS induced colitis, colonic IL-6, TGF-β, and IFN-γ were also significantly increased in the TNBS-treated HSD mice, but IL-10 was decreased in the TNBS-treated HSD mice." (PMID 27926535, 2017). "Moreover, H. polygyrus infection in the course of dextran sulfate sodium (DSS) mediated colitis significantly exacerbates intestinal inflammation by amplifying the release of colonic IL-6 and CXCL1." (PMID 28938014, 2017). "Additionally, DHA and EPA treatment during the recovery process effectively alleviated the severity of colitis, reduced immune cell infiltration, and inhibited IL-6 production." (PMID 28800645, 2017). "In addition, studies using murine models of colitis and CD patients showed that inhibition of IL-6 signaling using antibodies improved the symptoms." (PMID 28179904, 2017). "IL-6, TNF-α, and IFN-γ are pathogenic mediators of murine colitis." (PMID 27110761, 2016). "The adrenalectomized mice with colitis had increased IL-6 levels in contrast to lower LPS in serum." (PMID 27403034, 2016).
colitis (continued). "In addition, the concentration of pro-inflammatory cytokines, in particular IFN-γ, TNF-α and IL-6 secreted by total LP cells in the colon, was two- to sixfold higher in IL-15-deficient mice with CD4+ T-cell-driven colitis compared with RAG2ko host mice." (PMID 26964669, 2016). "In addition to macrophages, epithelial cells are also involved in driving the inflammatory cascade by secreting IL-6 in both patients and animal models of colitis." (PMID 26083103, 2015). "Ac-food showed the highest expression of TNF-α and IL-6, which might be related to the severity of colon inflammation." (PMID 26140540, 2015). "Our data demonstrate that both the HAS1/HAS3 double and the HAS3 null mice are protected from colitis, compared to wild-type and HAS1 null mice, as determined by measurement of weight loss, disease activity, serum IL-6 levels, histologic scoring, and immunohistochemistry." (PMID 26448758, 2015). "DSS-induced colitis enhanced the circulating levels of IL-6, TNF-α and GRO-α31." (PMID 26066467, 2015). "In our study, the RT-PCR assay exhibited that the mRNA levels of TNF-α, IL-1β, and IL-6 were greatly reduced by CBS in DSS-induced colitis mice, suggesting that the protective effect of CBS against colonic injury is related to the regulation of TNF-α, IL-1β, and IL-6." (PMID 26579201, 2015). "The aim of this study was to evaluate the action of glucans from the Caripia montagnei model on 2,4,6-trinitrobenzene sulfonic acid (TNBS)-induced colitis in rats and their effects on interleukin levels (IL-1 IL-6), catalase, myeloperoxidase (MPO) enzymes and nitric oxide." (PMID 24518681, 2014). "Similarly, the administration of a neutralizing IL-21 antibody to DSS-colitis mice decreased the colonic T-cell infiltrate and the production of IL-6 and IL-17A in the inflamed colonic tissue." (PMID 25101191, 2014). "Therefore, elevated levels of local TGF-β1 and IL-6 in colitis can be correlated with inflammatory events, fibrosis and structuring of the disease." (PMID 24465791, 2014). "However, an earlier study reported reduced colitis and mortality after DSS administration in Il-6-deficient mice compared to wild-type (wt) mice." (PMID 24993179, 2014). "IL-6 is generated in dnKO mice soon after colitis induction." (PMID 25478789, 2014). "At this point of understanding, it would be reasonable to breed double-deficient mice, which express neither IL-6 nor IL-6R (Il-6−/−/Il-6r−/−), and challenge them in comparison with Il-6−/−/Il-6r+/+, Il-6+/+/Il-6r−/− and Il-6+/+/Il-6r+/+ mice in a model of DSS-induced colitis." (PMID 24993179, 2014). "Consistently, we found that the TTP KO mice treated with DSS displayed increased susceptibility to colitis, decreased colon length, and increased neutrophil infiltration and expression of pro-inflammatory cytokines such as TNF-α, IL-6, CXCL1, and CXCL2 in the large intestinal mucosa." (PMID 24586391, 2014). "One important factor is IL-6, which has been shown to be upregulated in colitis." (PMID 24993179, 2014). "Finally, IL-6 has been identified in several cell types within tumors of mice with colitis-induced cancer including epithelial cells, CD4+ cells, and monocytes." (PMID 25478789, 2014). "The exact mechanisms behind the protumor effect of NF-κB/IL-6 in colitis associated carcinogenesis are not fully understood thus far." (PMID 25093140, 2014). "Development and remission of DSS-induced colitis in mice was determined by weight measurements and histology scores, and by quantification of expression of pro- (IL-1β, IL-6 and IFNγ) and anti-inflammatory (IL-10) cytokines, the chemokine CXCL1 and the inducible nitric oxide synthase." (PMID 24401855, 2014). "Pro-tumorigenic cytokines such as IL-1β, IL-6 and MIP-2 production as well as INF-γ and TNF production at the lamina propria were increased in the setting of colitis, and further in tumor tissues in associations with up-regulated TNFR2 and MLCK expressions in the epithelial cells of a CAC model." (PMID 24520376, 2014).